RETREG1 (reticulophagy regulator 1)
Description:
Endoplasmic reticulum (ER)-anchored autophagy regulator which mediates ER delivery into lysosomes through sequestration into autophagosomes. Promotes membrane remodeling and ER scission via its membrane bending capacity and targets the fragments into autophagosomes via interaction with ATG8 family proteins. Active under basal conditions. Required for collagen quality control in a LIR motif-dependent manner (By similarity). Required for long-term survival of nociceptive and autonomic ganglion neurons. (Microbial infection) During SARS-CoV-2 infection, RETREG1-mediated reticulophagy is promoted by SARS-CoV-2 ORF3A protein. This induces endoplasmic reticulum stress and inflammatory responses and facilitates viral infection.
Synonyms: FAM134B; JK1; FLJ20152; JK-1
Tractability: Antibody: UniProt predicts a signal peptide or a membrane-spanning region. PROTAC: ubiquitination databases record sites on it.
Gene: Protein-coding gene on chromosome 5 (16,473,038 to 16,617,101, reverse strand). Ensembl gene ENSG00000154153.
Subcellular location: Golgi apparatus, cis-Golgi network membrane; Endoplasmic reticulum membrane
Subcellular location (Human Protein Atlas): Endoplasmic reticulum
Pathways (Reactome):
Disease: Dengue virus modulates apoptosis
Gene Ontology:
Molecular function: protein binding; endoplasmic reticulum-autophagosome adaptor activity
Biological process: negative regulation of neuron apoptotic process; reticulophagy; sensory perception of pain; substrate localization to autophagosome
Cellular component: endoplasmic reticulum; endoplasmic reticulum membrane; cis-Golgi network; Golgi apparatus
Genetic constraint (gnomAD): Loss-of-function variants: 24 observed, 40.03 expected, observed/expected ratio (o/e) 0.6, 90% interval 0.43 to 0.84. The upper end of that interval is the gene's LOEUF score, 0.84, which puts it in group 3 of 6, group 1 being the genes least tolerant of losing a copy. Missense variants: 363 observed, 458.12 expected, observed/expected ratio (o/e) 0.79, 90% interval 0.73 to 0.86. Synonymous variants: 128 observed, 161.34 expected, observed/expected ratio (o/e) 0.79, 90% interval 0.69 to 0.92.
Gene-disease validity (ClinGen):
ClinGen rates the evidence that RETREG1 causes each of these diseases.
hereditary sensory and autonomic neuropathy (autosomal recessive): Definitive. An instance of sensory peripheral neuropathy that is caused by an inherited modification of the individual's genome.
Homologues: Orthologues: chimpanzee RETREG1 (99% identical), macaque RETREG1 (99% identical), pig RETREG1 (90% identical), mouse Retreg1 (87% identical), rabbit RETREG1 (86% identical), guinea pig RETREG1 (77% identical), tropical clawed frog retreg1 (48% identical).
Diseases named in the same sentence as RETREG1 in open-access papers:
RETREG1 is named in the same sentence as 71 diseases in open-access papers, as found by Europe PMC text mining. Sharing a sentence is not in itself a finding about the gene and the disease. The quoted sentences say what the papers report.
esophageal squamous cell carcinoma (14 papers, 2014 to 2025). Esophageal squamous cell carcinoma (ESCC) is a type of esophageal carcinoma (EC) that can affect any part of the esophagus, but is usually located in the upper or middle third. "Fam134b (JK‐1, RETREG1) was first identified as an oncogene in esophageal squamous cell carcinoma." (PMID 30556279, 2019). "Family with sequence similarity 134, member B (FAM134B), also known as RETREG1 or JK1, was initially identified as an oncogene in esophageal squamous cell carcinoma (ESCC)." (PMID 41198618, 2025). "FAM134B (also called JK-1, RETREG1), a member of the family with sequence similarity 134, was originally discovered as an oncogene in esophageal squamous cell carcinoma." (PMID 33199694, 2020).
Sensory neuropathy (9 papers, 2016 to 2023). Peripheral neuropathy affecting the sensory nerves. "A human form homologue of the sensory neuropathy of the Border Collie is known and called HSAN2B, where a mutation of the FAM134B/RETREG1 gene is also described." (PMID 35324855, 2022). "Little is known about FAM159A, but FAM134B, aka RETREG1 reticulophagy regulator 1, has a substantial literature connecting it with various functions including autophagy, and sensory neuropathy in humans and Border Collies." (PMID 33115496, 2020).
colorectal cancer (8 papers, 2016 to 2024). A primary or metastatic malignant neoplasm that affects the colon or rectum. "In the five types of controversial cancers (NSCLC, bladder cancer, prostate cancer, colorectal cancer, pancreatic cancer), several reports showed miR-186 served as an oncomir by suppressing targets PTEN, PPM1B, RETREG1, AKAP12, or NR5A2." (PMID 32195180, 2020).
autonomic neuropathy (6 papers, 2019 to 2025). An inherited or acquired peripheral neuropathy affecting the autonomic nervous system. "In another study we found one of the strongest signals of selection in the Yakut cattle, adapted to survive at − 50 °C, in the area of the gene RETREG1, one of the key genes involved in the hereditary sensory and autonomic neuropathy, type II in humans." (PMID 32039702, 2019).
viral infection (5 papers, 2020 to 2024). "In the context of viral diseases, other studies have highlighted the relationship between the absence of the RETREG1 protein and heightened replication of Dengue and Zika viruses." (PMID 38034497, 2023).
glioblastoma (4 papers, 2022 to 2023). The most malignant astrocytic tumor (WHO grade IV). "The autophagic cell death- (ACD-) triggering compound loperamide induced reticulophagy and cell death that are predominantly mediated through the reticulophagy receptor RETREG1/FAM134B and TEX264, which together promote proliferation of glioblastoma cells ACD." (PMID 35837377, 2022).
hereditary sensory and autonomic neuropathy (4 papers, 2018 to 2021). "The RETREG1 is responsible for human pain insensitivity disorder caused by hereditary sensory and autonomic neuropathy (HSAN)." (PMID 30154520, 2018).
Sepsis (3 papers, 2021 to 2026). Sepsis is defined as life-threatening organ dysfunction caused by a dysregulated host response to infection. "Here, we report the key role of reticulophagy regulator 1 (RETREG1), a selective autophagy receptor, in maintaining DC maturation and function in the early stage of sepsis." (PMID 41874459, 2026). "Consequently, Cd11ccreRetreg1fl/fl, Retreg1-/-, and Atf6-/- mice exhibit impaired DC function, leading to immunosuppression and multiple organ failure in experimental sepsis." (PMID 41874459, 2026).
amyotrophic lateral sclerosis (2 papers, 2021 to 2024). Amyotrophic lateral sclerosis (ALS) is a neurodegenerative disease characterized by progressive muscular paralysis reflecting degeneration of motor neurons in the primary motor cortex, corticospinal tracts, brainstem and spinal cord. "Some patients with mutations in RETREG1 suffer from cardiac arrhythmia, an‐ or hypohydrosis and other symptoms of autonomic malfunctions overlapping with amyotrophic lateral sclerosis (ALS) and myopathies." (PMID 34459017, 2021).
intervertebral disc degeneration (2 papers, 2022 to 2024). "Recent studies in a model of intervertebral disc degeneration (IDD), demonstrate that family with sequence similarity 134 member B (FAM134B; RETREG1) protein abundance, and in turn ER-phagy, is impacted by O-GlcNAcylation." (PMID 38641064, 2024).
COVID-19 (1 paper, 2025). A disease caused by infection with severe acute respiratory syndrome coronavirus 2. "RETREG1, along with FNDC4, also inhibits SARS-CoV-2 viral replication, suggesting that components of the ERAD pathway may serve as inhibitors of COVID-19 BIs." (PMID 40650217, 2025).
viral myocarditis (1 paper, 2025). Myocarditis that is caused by an infection with a viral agent. "Secondly, we uncovered novel loci (e.g., RETREG1 and VWDE) and pathways, such as viral myocarditis and lipid metabolism, broadening the understanding of biological mechanisms underlying BIs." (PMID 40650217, 2025).
cancer (22 papers, 2016 to 2025). A tumor composed of atypical neoplastic, often pleomorphic cells that invade other tissues. "Islam F., Gopalan V., Lam A.K. RETREG1 (FAM134B): a new playerin human diseases: 15 years after the discovery in cancer." (PMID 34901717, 2021).
infection (9 papers, 2020 to 2024). The state of being infected such as from the introduction of a foreign agent such as serum, vaccine, antigenic substance or organism. "In the Alpha and BA.5 variants, RETREG1 expression remains consistently downregulated and continues to decrease over time, while in other variants there is a resurgence of rising expression in the middle or later stages of infection." (PMID 39653747, 2024).
RETREG1 also shares sentences with these, for which no sentence is quoted: tumor (22 papers); breast cancer (9); hepatocellular carcinoma (9); colon cancer (7); liver cancer (3); lung carcinoma (3); melanoma (3); neuropathy (3); preeclampsia (3); adenoma (2); allergic rhinitis (2); cardiovascular disease (2); lymph node metastasis (2); microphthalmia (2); neurological diseases (2); acquired immunodeficiency syndrome (1); Alzheimer disease (1); asthma (1); Atrophy (1); bacterial infection (1); cardiac hypertrophy (1); cervical cancer (1); chronic myeloid leukemia (1); colitis (1); colorectal adenoma (1); dengue (1); developmental delay (1); Distal sensory impairment (1); epilepsy (1); Epileptic encephalopathy (1).
A further 27 diseases each share a sentence with RETREG1 in 1 paper.